IL21 (interleukin 21)
Diseases named in the same sentence as IL21 in open-access papers (continued):
Sharing a sentence is not in itself a finding about the gene and the disease.
colitis (continued). "Furthermore, blockade of IL-21 using a specific IL-21R-fusion protein improves intestinal inflammation and downregulates Th17 responses during the course of DSS colitis." (PMID 31886308, 2019). "However, they also showed that CS exposure increased mRNA expression of inflammatory cytokines including TNF, IFN-γ, IL-17, and IL-21 in Ja18−/− mice and escalated clinical symptoms of DSS-induced colitis in CD1d−/− mice." (PMID 29163466, 2017). "Similarly, IL-21 expression is high in the gut of mice with dextran sulphate- (DSS-) induced colitis, whereas Il21−/− mice showed reduced DSS-colitis, lower inflammatory cell infiltration, and IL-17 production." (PMID 25961061, 2015). "However, it is worth noting that the ICOS/IL-21/auto-Ab–mediated organ toxicity is not necessarily applicable to all irAE pathologies, such as colitis." (PMID 40198121, 2025). "It was hypothesized that IL-21 would be required for the optimal expression of IL-12Rβ2, but not IL-12Rβ1, in CD4+ T cells, thereby regulating a TH1-biased immune profile following colon inflammation." (PMID 38498592, 2024). "We have observed a negative relationship between Blimp-1 and IL-21 in our previous reports: overexpression of Blimp-1 in T cells suppresses autoimmune diabetes whereas lack of Blimp-1 in T cells results in severe colitis in NOD mice." (PMID 35503415, 2022). "Although neutralization of IL-17A was not effective in the relief of colitis in a mouse model or in a clinical study of CD patients, another Th17-type cytokine, IL-21, also has pro-inflammatory effects and may be a suitable therapeutic target." (PMID 31767028, 2019). "However, the role of the IL-21/IL-21R signaling axis in colitis of any origin and in collaboration with IFN-γ is not known." (PMID 30818341, 2019). "Similarly, immunodeficient mice adoptively transferred with CD4+IL-21−/− T cells develop less severe colitis, and mice treated in a prophylactic setup with a neutralizing IL-21R/Fc fusion protein or anti-IL-21 mAb are protected from both DSS and TNBS-induced colitis." (PMID 29849593, 2018). "Collectively, these findings indicated a novel and previously unknown role played by IL-21/IL-21R signaling in driving CD4+ T-cell responsiveness to IL-12 by enhancing the expression of IL-12Rβ2 in CD4+ T cells, thereby imprinting a TH1-biased immunity during bacterial-induced colitis." (PMID 38498592, 2024). "In our piroxicam-accelerated colitis study, where colitis symptoms are more acute and not directly driven by CD4 T cells, we did not observe any protective effect of IL-21 neutralization." (PMID 29849593, 2018).
type 1 diabetes (46 papers, 2008 to 2026). "Blimp-1 and IRF4 can be activated by factors other than B cell receptor signalling, such as IL-21 and IL-6 or IFNα and IL-6, cytokines implicated in the pathogenesis of type 1 diabetes." (PMID 36508037, 2023). "The strongest effect on age at onset of any region outside the HLA region is the IL21 gene region, which has a relatively small effect on risk of type 1diabetes itself." (PMID 31438962, 2019). "Taken together, these data indicate that our observed increase in the frequency of IL-21+-producing cells within the CD45RA− memory Teff cell subset is not caused by an altered composition of the CD45RA− memory Teff compartment in type 1 diabetes patients." (PMID 25652388, 2015). "A report describing novel sequence variants in genes encoding IL-21 and the IL-21R indicates that polymorphisms within IL-21 and the IL-21 receptor are positively associated with type 1 diabetes in humans." (PMID 26416419, 2015). "A novel finding in this study was an association with several genes for IL-2 and IL-21 in chromosome 4q27, a region where SNPs associated with celiac disease and diabetes type 1 were also reported." (PMID 23843781, 2013). "For example, polymorphisms of IL-21 and its receptor were identified in patient samples associated with Type 1 diabetes." (PMID 18773086, 2008). "Interleukin (IL)-21 and IL-22 have been implicated in the pathogenesis of type 1 diabetes mellitus (T1DM)." (PMID 40422866, 2025). "Similarly, in non-obese diabetic (NOD) mice which have genetic polymorphisms in the il2 gene locus and lower IL-2 production, IL-21 plays a critical role in sustaining pathogenic auto-immune responses that lead to development of type-1 diabetes (T1D) in these mice." (PMID 24416451, 2014). "In a type 1 diabetes model, IL-21 regulates antigen transport in DCs, facilitating the acquisition of C-C chemokine receptor 7 (CCR7), thereby promoting their migration to draining lymph nodes." (PMID 40376002, 2025). "In this study, our aim was to examine plasma IL-21 levels in individuals at different stages of type 1 diabetes progression." (PMID 37415982, 2023). "Adults with established type 1 diabetes had higher plasma IL-21 levels compared to healthy controls." (PMID 37415982, 2023). "Type-1 diabetes prone NOD mice harbor an increased number of IL-21-producing CCR9+ Th cells in the inflamed lesions of the pancreas and salivary glands that are phenotypically similar to Tfh cells." (PMID 30662436, 2018). "IL-21 has a potential role in other inflammatory and autoimmune disorders, such as type 1 diabetes, allergy, and asthma, and inflammatory disorders such as the spondyloarthropathies." (PMID 28427414, 2017). "It is of particular importance for type 1 diabetes, as IL-21 production is increased in type 1 diabetic patients, and resulting B cell involvement in disease progression seems likely." (PMID 28125737, 2017). "Since IL-21 production is characteristic of Tfh cells, we examined the frequency of this subset in whole blood samples from an independent cohort of 30 type 1 diabetes patients and 32 healthy donors." (PMID 25652388, 2015). "It is plausible that the increased frequency of circulating Tfh cells is directly responsible for the increased IL-21 production observed in type 1 diabetes patients." (PMID 25652388, 2015). "In the present study, following in vitro stimulation, we detected an increased proportion of IL-21-producing cells within the memory CD4+ Teff population in type 1 diabetes patients." (PMID 25652388, 2015). "Consistent with the increased production of IL-21, we also report an increased frequency of peripheral Tfh from an independent cohort of 30 long-standing type 1 diabetes patients and 32 healthy controls." (PMID 25652388, 2015).
type 1 diabetes (continued). "As a consequence, the demonstration of increased IL-21 production in type 1 diabetes patients supports the findings from genetic studies of type 1 diabetes implicating a dysfunction of the IL-2 signalling pathway in the pathogenesis of the disease." (PMID 25652388, 2015). "We found a 21.9% (95% CI 5.8, 40.2; p = 3.9 × 10−3) higher frequency of IL-21+ CD45RA− memory CD4+ Teffs in patients with type 1 diabetes (geometric mean 5.92% [95% CI 5.44, 6.44]) compared with healthy donors (geometric mean 4.88% [95% CI 4.33, 5.50])." (PMID 25652388, 2015). "Collectively, these findings suggest that Tfh cells and IL-21-mediated inflammation are involved in the pathogenesis of type 1 diabetes." (PMID 25652388, 2015). "In summary, we have identified an imbalance in IL-21 production in type 1 diabetes patients, which is accompanied by an increased frequency of circulating Tfh cells." (PMID 25652388, 2015). "This suggests that the combination of anti-IL-21 antibody and liraglutide may help protect β-cell function in adults with recent-onset type 1 diabetes, with good safety, and warrant further evaluation." (PMID 40376002, 2025). "This demonstrates that IL-21/IL-21R signaling is essential for DC migration in virus-induced type 1 diabetes, but whether this applies to transplantation requires further validation." (PMID 40376002, 2025). "In addition, overexpression of IL-21 neutralises the suppressive capability of Treg cells with the development of type 1 diabetes." (PMID 37432371, 2023). "Correspondingly, overexpression of IL-21 in pancreatic β-cells induced inflammatory cytokines and chemokines and ensued leukocytic infiltration in the islets, resulted in destruction of β-cells and spontaneous type 1 diabetes of C57/BL6 mice." (PMID 35693111, 2022). "Furthermore, CD4 T follicular helper (Tfh) cells in patients with type 1 diabetes have increased IL-21 production, compared to healthy donors." (PMID 34616408, 2021). "IL-21 has been proposed as an attractive target in type 1 diabetes." (PMID 33595677, 2021). "Intriguingly, GLP-1 analogues in combination with a monoclonal anti-interleukin-21 antibody may, in turn, be useful to delay disease progression of type 1 diabetes when therapy is initiated shortly after diagnosis." (PMID 35602193, 2021). "Interestingly, naïve B cell responses to IL-21 are diminished in established human type 1 diabetes; however this response is enhanced in pre-diabetic individuals with multiple islet autoantibodies." (PMID 34616408, 2021). "Other type 1 diabetes-associated regions that contribute are the INS, IL21 and CTSH gene regions." (PMID 31438962, 2019). "One of the strongest type 1 diabetes associated loci, PTPN22, may also be implicated in Tfh cell responses and IL-21 production leading to an increase in B cell numbers and antibody production in Ptpn22 knockout mice." (PMID 25652388, 2015). "Interestingly, B cell depletion with a course of anti-CD20 therapy (rituximab) decreased circulating IL-21 levels and the frequency of Tfh cells in peripheral blood of type 1 diabetes patients, and preserved beta cell function in ten out of 20 patients." (PMID 25652388, 2015). "Overall, our findings underscore an inherent bias towards a proinflammatory response in type 1 diabetes patients and potentially reflect alterations of the immune system observed in the autoimmune microenvironment, which are critically dependent on IL-21 signalling." (PMID 25652388, 2015). "To investigate the potential association between frequency of circulating Tfh cells and IL-21+ memory T cells, we measured IL-21 production in cryopreserved PBMCs from 46 (24 type 1 diabetes patients and 22 healthy controls) of the 62 individuals who had been assessed for Tfh frequency." (PMID 25652388, 2015).
type 1 diabetes (continued). "Moreover, Lebailly and colleagues hypothesised that the clock gene ARNTL2 specifically is a candidate gene for type 1 diabetes as it controls expression of the IL21 gene, and the IL-21 cytokine is necessary for the development of diabetes in the NOD mouse." (PMID 34003304, 2021). "Thus, the IL21 score for type 1 diabetes was strongly associated with early age at onset but not with low C-peptide level." (PMID 31438962, 2019). "Both type I IFNs and IL-21 regulate SOCS1 expression in T cells and both regulate the development of type 1 diabetes in NOD mice." (PMID 31653894, 2019). "We assessed the production of the proinflammatory cytokines IL-21, IFN-γ and IL-17 in peripheral blood mononuclear cells from 69 patients with type 1 diabetes and 61 healthy donors." (PMID 25652388, 2015). "In the present study, we have characterised the production of the key proinflammatory cytokines IL-21, IL-17 and IFN-γ in the peripheral T cell compartment of 69 type 1 diabetes patients and 61 healthy donors." (PMID 25652388, 2015). "The pleiotropy and the wide range of action of IL-21 on the components of the immune system have placed this cytokine in the central axis of various pathologies such as cancer and immune-mediated diseases like MS, RA, SLE, or type 1 diabetes." (PMID 35902536, 2022). "Reassuringly, non-clinical models, including a viral type 1 diabetes model, showed a minor impact of IL-21 blockade on the immune repertoire." (PMID 33595677, 2021). "We measured the production of three major proinflammatory cytokines, IL-21 (n = 114), IL-17 (n = 66) and IFN-γ (n = 116), by polychromatic flow cytometry in type 1 diabetes patients and healthy controls, matched as closely as possible for age, sex and time of sample preparation." (PMID 25652388, 2015). "The data herein also indicate that blocking the interleukin 21/4 and/or CD40L might be of therapeutic interest in CLL, especially in the light of the minimal toxicity of such approaches in type 1 diabetes, asthma and multiple sclerosis therapy trials, respectively." (PMID 38877102, 2024). "Interestingly, IL-21 activity is increased in Helicobacter pylori infection, leading to higher production of matrix metalloproteinases MMP2 and MMP9, and MMP2 and MMP9 have been shown to be upregulated in Type 1 diabetes." (PMID 18773086, 2008). "Furthermore, genetically higher plasma levels of IL‐21 and MICB are associated with an elevated risk of digestive disorders such as intestinal malabsorption and endocrine metabolic disorders including Type 1 diabetes, thyrotoxicosis with or without goiter, and Graves' disease." (PMID 38730525, 2024). "We report here an increased production of IL-21 and, to a lesser extent, IL-17, but not IFN-γ, in memory CD4+ T effector (Teff) cells from type 1 diabetes patients as compared with healthy controls." (PMID 25652388, 2015). "In contrast to IL-21, there was no convincing support for a differential frequency of IFN-γ-producing cells within the CD45RA− CD4+ T cell subset (p = 0.07) in type 1 diabetes patients as compared with controls." (PMID 25652388, 2015).
melanoma (42 papers, 2006 to 2025). A malignant, usually aggressive tumor composed of atypical, neoplastic melanocytes. "Using another approach, by fusion of highly attenuated IL-21 mutein variant (R9E:R76A) to the C-terminus of the anti-PD-1 antibody, a bifunctional protein was obtained which provided protection in a human melanoma mouse model resistant to anti-PD-1 therapy." (PMID 38638431, 2024). "Although, both routes of administration of IL-21, subcutaneous (s.c.)or i.p., induced antitumor effects in mice bearing established melanoma or renal cell carcinoma, only s.c. route inhibited the growth of large tumors." (PMID 38638431, 2024). "Administration of IL-21-induced CD8+ T cells into human melanoma-bearing mice led to the cessation of the tumor growth." (PMID 38638431, 2024). "Kim-Schulze and co-workers applied Lipofectamine 2000 for the introduction of IL-21 genes into the melanoma cells for the purpose of providing the sustained and local production of IL-21." (PMID 36742134, 2023). "Utilizing our mixed BMC model, melanoma tumor-bearing mice were adoptively transferred with IL-21-producing CD4+ T cells." (PMID 33809259, 2021). "Results are expected from clinical trials evaluating the safety and efficacy of combining IL-21 with other immunotherapeutic mediators: IL-21/anti-PD-1 against solid tumors (NCT01629758) and IL-21/ipilimumab against melanoma (NCT01489059)." (PMID 34025641, 2021). "Our group has previously shown that IL-21-producing CD4+ T cells provide critical help to promote the generation of effector CX3CR1+ CD8+ T cells in a preclinical melanoma model." (PMID 33809259, 2021). "For example, several ODE systems were devised to model melanoma with Th1 and Th2 helper lymphocytes, with natural killer cells (NK) in the context of interleukin 21 (IL21) therapy, with M1 and M2 macrophages, or both macrophages and helper lymphocytes." (PMID 32410672, 2020). "Recombinant IL-21 given to melanoma and MethA fibrosarcoma mice models delayed tumor progression via increased number of anti-tumor CTLs." (PMID 31024571, 2019). "For human CD8+ T cells isolated from the peripheral blood of healthy donors, IL-21 promotes Tscm development in vitro leading to improved immunity upon adoptive transfer into mice with melanoma compared to IL-2-stimulated CD8+ T cells." (PMID 30842774, 2019). "In a phase 1 clinical trial using recombinant human IL-21 (rhIL-21) in a dose-escalation study with 43 patients (24 melanoma and 19 renal cell carcinoma patients), rhIL-21 was administered consecutively for 5 days for two full cycles." (PMID 30842774, 2019). "In fact, recombinant IL-21 has been utilized in early clinical trials in cancer patients with e.g. melanoma or colorectal cancer and observations indicate an enhanced T-cell activity." (PMID 29568345, 2018). "A preclinical study using an IL-21 plasmid expression system in melanoma and fibrosarcoma treatment, showed potent antitumor effect and increased survival rate of tumor-bearing mice." (PMID 28927416, 2017). "In clinic, phase I and II trials for IL-21 as single-agent, revealed a modest response of patients with melanoma." (PMID 28927416, 2017). "Clinical trials using IL-21 as a single agent in melanoma and renal cell carcinoma show that this cytokine is well tolerated and favorable clinical responses have been observed as evidenced by patients in which disease stabilized." (PMID 27656185, 2016). "Another phase I study tested subcutaneous IL-21 at three doses per week for 8 or 16 weeks, in melanoma and renal cancer patients." (PMID 25961061, 2015). "In a syngeneic melanoma model a tumor cell vaccine that displayed membrane-anchored glycosylphosphatidylinositol- (GPI-) IL-21 delayed tumor growth and prolonged mice survival." (PMID 25961061, 2015). "Similar rejection responses, involving CTL and/or NK cells, were observed for IL-21-secreting melanoma, fibrosarcoma, colon, renal, and bladder cancer cells." (PMID 25961061, 2015).